TOP1 (DNA topoisomerase I)
Diseases named in the same sentence as TOP1 in open-access papers (continued):
Sharing a sentence is not in itself a finding about the gene and the disease.
glioblastoma (7 papers, 2015 to 2025). The most malignant astrocytic tumor (WHO grade IV). "Synergistic combinatorial effects have been confirmed recently for TOP1 and PARP inhibitors in glioblastoma cells, especially in PTEN-null lines." (PMID 40439882, 2025). "TOP1/TOP2A and PARP poisons are already an important component of many treatment protocols for glioblastoma, sarcoma and other ALT + tumour types." (PMID 36940725, 2023). "Cultured human glioblastoma U87 cells, which normally do not express L1, were transduced with lentivirus, encoding the recombinant MIF-EGFP gene, for 48 h, then the cells were further transduced with adeno-associated virus mediating the expression of L1-70-Myc and Top1-HA for an additional 24 h." (PMID 35013124, 2022).
cervical cancer (6 papers, 2019 to 2025). A primary or metastatic malignant neoplasm involving the cervix. "In vitro, TOP1 knockdown suppressed cervical cancer cell growth, reduced their migration, and limited their invasion." (PMID 41142804, 2025). "Specifically, the expression of TOP1 was upregulated in cervical cancer and correlated with poor prognosis." (PMID 41142804, 2025). "A recent study demonstrated that HPV oncoproteins E6 and E7 upregulated topoisomerase I (TOP1) expression to activate the cGAS-PD-L1 pathway, consequently promoting cervical cancer development." (PMID 41142804, 2025). "Inhibitors of DNA topoisomerase I (TOP1), an enzyme relieving torsional stress of DNA by generating transient single-strand breaks, are clinically used to treat ovarian, small cell lung and cervical cancer." (PMID 31242600, 2019).
liver cancer (5 papers, 2018 to 2025). An epithelial or non-epithelial malignant neoplasm that arises from the liver. "circIPO11 recruits TOP1 to GLI1 promoter to activate its transcription, and drives self-renewal of liver cancer initiating cells." (PMID 36747292, 2023). "TOP1 and TOP2A are key tumor drivers in liver cancer 24, suggesting that TOP1 and TOP2A might be promising targets for treating malignances." (PMID 31956371, 2020).
lymphoma (5 papers, 2011 to 2019). A malignant (clonal) proliferation of B- lymphocytes or T- lymphocytes which involves the lymph nodes, bone marrow and/or extranodal sites. "Top1 expression levels have previously been correlated with cellular sensitivity to camptothecins; low levels of Top1 confer resistance to cancer cell lines such as lymphomas." (PMID 21573211, 2011). "In fact, combination therapy with PARP and Top1 inhibitors, including dual treatment with CPT11 and olaparib, has potential in human cancer treatment and is already being investigated in patients with various types of tumors and lymphomas." (PMID 28158293, 2017).
bladder cancer (4 papers, 2013 to 2023). "Hydroxycamptothecin (HCPT) is a DNA topoisomerase I inhibitor, which has been utilized in chemotherapy for bladder cancer for nearly 40 years." (PMID 23365634, 2013). "Thus, our current data further demonstrated that the differential effect of FL118 on the three bladder cancer cell lines is irrelevant to Top1 expression." (PMID 33217967, 2020). "In contrast to these findings for CPTs, the FL118-sensitive bladder cancer cell lines (T24, UMUC-3) resulted in the least Top1 expression after FL118 treatment, while the FL118-resistant HT1376 cell line still had a substantial level of Top1 expression after FL118 treatment." (PMID 33217967, 2020). "Moreover, pulldown assays and computer simulation technology were used to capture the molecules that may directly interact with JorA in bladder cancer cells, such as fatty acid synthase (FASN) and DNA topoisomerase 1 (Top1), which participate in the biological process of JorA inhibiting MIBC cells." (PMID 37587470, 2023).
metastatic colorectal cancer (4 papers, 2014 to 2023). "Irinotecan (CPT-11) is a TOP1 inhibitor, which plays an important role in clinical treatment of metastatic colorectal cancer." (PMID 37386467, 2023). "Irinotecan, a broad-spectrum DNA topoisomerase I inhibitor, has been used as a first-line treatment in combination with 5-Fu/leucovorin for metastatic colorectal cancer." (PMID 30733972, 2019). "We examined the copy numbers (CN) of topoisomerase I (TOP1) as well as the ratios of TOP1/CEN-20 and TOP1/CEN-2 as biomarkers for irinotecan efficacy in patients with metastatic colorectal cancer." (PMID 28077117, 2017).
pancreatic cancer (4 papers, 2017 to 2025). "Similarly, MSI2 and HIST1H1C have been associated with metastasis of pancreatic cancer, while TOP1 is associated with metastatic breast cancer." (PMID 41301029, 2025). "Using patient-derived xenografts of KRAS- and MYC-driven pancreatic carcinoma, we show that coinhibition of topoisomerase 1 (TOP1) and bromodomain-containing protein 4 (BRD4) synergistically induces tumor regression by targeting promoter pause release." (PMID 37831776, 2023). "This preclinical study provides a mechanistic understanding of the benefit of combining TOP1 and BRD4 inhibitors to treat pancreatic carcinomas addicted to oncogenic drivers of transcription and replication." (PMID 37831776, 2023). "Together, these results suggest that targeting transcription via dual inhibition of TOP1 and BRD4 can specifically target KRAS- and MYC-driven pancreatic tumors and provide viable and clinically applicable therapy for hard-to-treat cancer entities such as PDAC and panNEC." (PMID 37831776, 2023). "TOP1 and BRD4 drugs synergize to kill pancreatic cancer in vivo via readthrough transcription without emergent drug resistance." (PMID 37831776, 2023).
sarcoma (4 papers, 2022 to 2025). A usually aggressive malignant neoplasm of the soft tissue or bone. "Interestingly, the expression levels of KLRB1 and TOP1 were significantly associated with the survival of sarcoma patients (p < 0.05), indicating that they could be potential prognostic markers." (PMID 36118864, 2022). "Altogether, these results demonstrated that EwS is significantly more sensitive to TOP1 poisons than other tested sarcoma models, both in vitro and in vivo." (PMID 40721661, 2025).
ataxia telangiectasia (3 papers, 2013 to 2020). Ataxia-telangiectasia is the association of severe combined immunodeficiency (affecting mainly the humoral immune response) with progressive cerebellar ataxia. "It is also consistent with recent reports that the repair of TOP1-induced SSBs is reduced in ataxia telangiectasia; the archetypal neurodegenerative disease associated with defects in DNA strand break repair." (PMID 32504494, 2020). "Together, these data identify a distinct role for ATM during the formation/resolution of neural Top1-CCs and suggest that their accumulation contributes to the neuropathology of ataxia telangiectasia." (PMID 23626666, 2013). "Accumulation of Top1-breaks during transcription has been associated with the neurological decline in SCAN1 and in other cerebellar degenerative hereditary disorders such as ataxia telangiectasia." (PMID 24335147, 2014). "We subsequently employed this assay to reveal an increased steady state level of Top1-CCs in neural cells lacking Atm; the protein mutated in ataxia telangiectasia." (PMID 23626666, 2013).
autism spectrum disorder (3 papers, 2016 to 2017). A spectrum of developmental disorders that includes autism, and Asperger syndrome. "Misregulation of TOP1 has been observed in neurodegenerative disorders and missense mutations and disruptions of genes that regulate TOP1 have been identified in individuals with autism spectrum disorders." (PMID 27231886, 2016). "The involvement of TOP1 in transcriptional regulation has recently become a focus in developing potential new treatments for a subtype of autism spectrum disorders." (PMID 27181710, 2016). "Interestingly, in addition to being widely used in cancer therapy, TOP1 poisons were recently shown to alleviate Angelman syndrome, a subtype of autism spectrum disorders (ASD) by suppressing the exceptionally long, antisense RNA transcript UBE3A-ATS." (PMID 27181710, 2016).
breast tumor (3 papers, 2016 to 2020). "An investigation of TOP1 gene copy number (including 1033 cases) based on use of the The Cancer Genome Atlas (TCGA) portal revealed that only 2% of breast tumors exhibited increased TOP1 copy number." (PMID 31783818, 2019). "Current data regarding TOP1 gene status in breast tumor tissue are rather controversial." (PMID 31783818, 2019).
cerebellar ataxia (3 papers, 2018 to 2023). A neurological syndrome characterized by clumsy and uncoordinated movement of the limbs, trunk, and cranial muscles. "TDP1 is a key factor for repairing TOP1-mediated PDBs and its mutation causes the demise of post-mitotic tissue and cerebellar ataxia in SCAN1." (PMID 29898404, 2018). "Bi-allelic TDP1H493R mutation is associated with ∼70% reduction of TDP1 protein level and leads to the accumulation of both TOP1- and TDP1-mediated PDBs, causing neurodegeration in spinocerebellar ataxia with axonal neuropathy 1 (SCAN1)." (PMID 29898404, 2018). "Similarly, if reduced DNA 5′-kinase activity is a cause of cerebellar ataxia and neurodegeneration in PNKP-mutated disease our results implicate SSBs arising from abortive TOP1 activity in AOA4 and CMT2B2, because this is a major source of DNA breaks with 5′-hydroxyl termini." (PMID 32504494, 2020).
esophageal cancer (3 papers, 2019 to 2024). A primary or metastatic malignant neoplasm involving the esophagus. "Through the transcripts list we found that TOP1 and TOP2 which were visualized as potential esophageal cancer therapeutic targets were highly enriched compared with the input group." (PMID 37088855, 2023). "The GEPIA2 database also indicated that TOP1 and TOP2 transcript levels were more highly expressed in the tumor tissues than adjacent tissues of the TCGA-Esophageal Cancer cohort patients." (PMID 37088855, 2023). "In the present study, esophageal cancer (FLO-1) cells treated with different anticancer drugs such as platinum-based DNA damaging agents (cisplatin), the DNA topoisomerase I inhibitors class of drugs (irinotecan), and 5-FU that interferes with thymidine nucleotide synthesis." (PMID 38697979, 2024).
Ewing sarcoma (3 papers, 1996 to 2025). A small round cell tumor that lacks morphologic, immunohistochemical, and electron microscopic evidence of neuroectodermal differentiation. "The topoisomerase 1 (TOP1) inhibitor irinotecan is a standard-of-care agent for relapsed Ewing sarcoma (EWS), but its efficacy is limited by chemical instability, rapid clearance and reversibility, and dose-limiting toxicities, such as diarrhea." (PMID 39512899, 2024).
glioma (3 papers, 2022 to 2024). A benign or malignant brain and spinal cord tumor that arises from glial cells (astrocytes, oligodendrocytes, ependymal cells). "We analyzed the TOP1 transcription factor FOSL2 of the C0 IGFBP7+ Glioma cells subgroup, which may be at the end of differentiation." (PMID 39403379, 2024).
lung adenocarcinoma (3 papers, 2021 to 2022). A carcinoma that arises from the lung and is characterized by the presence of malignant glandular epithelial cells. "Taken together, further research is required on SMARCC1, SMARCC2, and SMARCA5, together with TOP1, as predictive biomarkers of resistance to geldanamycin derivatives as HSP90 inhibitors in lung adenocarcinoma." (PMID 33802597, 2021).
lung fibrosis (3 papers, 2006 to 2020). "Although we demonstrated that the presence of detectable levels of mtDNA TOP1 was a constant and particular feature of SScFib+ patients, we did not fully ascertain the antigenic role of this protein fragment and its relation with the development of lung fibrosis." (PMID 17044913, 2006).
scleroderma (3 papers, 2011 to 2025). Scleroderma is a rare autoimmune connective tissue disorder characterized by abnormal hardening of the skin and, sometimes, other organs. "High titer TOP1 autoimmune antibodies are among the most common features of scleroderma and are associated with a poor prognosis and a high mortality rate as well." (PMID 27181710, 2016). "In many scleroderma tissues, there are also a decrease in TOP1 catalytic activity and an increase in TOP1 SUMOylation, but the nature of this SUMOylation and the significance of these phenomena to scleroderma pathogenesis are yet to be defined." (PMID 27181710, 2016). "Indeed, the degree of SUMOylation, such as in the case of TOP1, is significantly elevated in scleroderma tissues." (PMID 27181710, 2016). "The contribution of TOP1 to scleroderma is not limited to the production of α-TOP1 autoantibodies." (PMID 27181710, 2016). "P2 and P4 sera were obtained from patients with scleroderma withknown anti-topoisomerase I antibodies.42−46 MS analysis of the P2 serum immunoprecipitate showedthe presence of both cytoplasmic topoisomerase I (TOP1) and mitochondrialtopoisomerase 1 (TOP1MT), two highly homologous proteins." (PMID 39814365, 2025). "Since studies from our laboratory revealed that transcription-associated TOP1 K391 and K436 SUMOylation suppresses TOP1 activity while facilitating the TOP1–RNAPII interaction, it would be interesting to determine if TOP1 K391/K436 SUMO modification is deregulated in scleroderma." (PMID 27181710, 2016).
systemic sclerosis (3 papers, 2018 to 2020). A chronic disorder, possibly autoimmune, marked by excessive production of collagen which results in hardening and thickening of body tissues. "HLA-DRB1*11 expression has been associated to the rate of systemic sclerosis and promotes the induction of anti-DNA topoisomerase I Abs." (PMID 32854442, 2020).
behavioral disorders (2 papers, 2017 to 2025). "In addition, differentially methylated CG dinucleotides in LRP2BP, TOP1, NOSIP, and SEMA4B were associated with intellectual disability, behavioral disorders, disorders of psychological development, and schizophrenia spectrum disorders, respectively." (PMID 39460848, 2025).
brain cancer (2 papers, 2013 to 2023). A primary or metastatic malignant neoplasm affecting the brain. "Another interesting target identified was the TSPO -(Translocator protein) that is known to be expressed exclusively in brain cancers, including GBM, and can be used for delivering drugs across the blood brain barrier along with DNA topoisomerase I (TOP1), Lipoprotein Lipase (LPL), and DNMT1." (PMID 37637064, 2023).
carcinomas of the colon (2 papers, 2022 to 2023). "We previously showed that the colon carcinoma HCT116KI cell line, which has an exon 4 deletion in TOP1 preventing RNAPII-TOP1 interaction, without affecting the enzymatic activity of TOP1, exhibited greatly reduced synergy between SN38 and JQ1 compared to the isogenic wild-type cell line." (PMID 37831776, 2023).
colorectal tumors (2 papers, 2010 to 2019). "A preliminary study on nine clinical colorectal tumors indicated that the three samples with the highest TOP1 expression and activity were from patients who responded to irinotecan treatment." (PMID 31547492, 2019). "Finally, D20S107 is close to DNA topoisomerase I, a well-established molecular target of anticancer drugs, such as camptothecin derivatives, which are approved by the FDA for the treatment of colorectal tumors." (PMID 20955588, 2010).
endometriosis (2 papers, 2024 to 2025). The growth of functional endometrial tissue in anatomic sites outside the uterine body. "The model with the lowest AIC and highest AUC was a 4-protein model including TOP1, HIST1H3A, IGFBP1, and CD5L which discriminated endometriosis cases from controls with an AUC = 0.71 (95%CI = 0.66–0.76) from the conditional logistic regression model." (PMID 40215752, 2025). "Moreover, cyto-hub gene analysis revealed that CSNK2A1, CSNK2A2, TOP1, PRKACA, RBM39 (plasma), ALB, ACTB, GAPDH, FN1, APOA1 (serum), S100-A9, CXCL1, IL1RN, CSTA, S100-A8 (menstrual blood) and THBS1, ALB, CD44, ANXA2, and LUM (urine) were the top 5 proteins expressed in women with endometriosis." (PMID 39061077, 2024).
interstitial lung disease (2 papers, 2020 to 2024). A diverse group of lung diseases that affect the lung parenchyma. "Antibodies against DNA topoisomerase I (ATA) are predictors of the development of interstitial lung disease (ILD) and digital ulcers but appear to be protective against PAH." (PMID 33168071, 2020).
malaria (2 papers, 2014 to 2016). Malaria is a serious and sometimes fatal disease caused by a parasite that commonly infects a certain type of mosquito which feeds on humans. "We demonstrated that the utilized DNA oligonucleotide substrates (in the present study termed the dumbbell substrates) were specifically circularized by their target enzymes e.g., DNA topoisomerase I from human (hTopI) or from the malaria parasite P. falciparum (pfTopI)." (PMID 27854277, 2016). "DNA topoisomerase I from Plasmodium falciparum (PfTopoI), a potential selective target for chemotherapy and drug development against malaria, is used here, together with human Topo I (HssTopoI), for docking, molecular dynamics (MD) studies and experimental assays." (PMID 24651068, 2014).
metastatic tumors (2 papers, 2018 to 2025). "Given frequent TOP1 expression in metastatic tumors and association with TOP2A expression, use of a TOP1 inhibitor in combination with a TOP2A inhibitor may be considered for recurrent and metastatic medulloblastomas." (PMID 29869738, 2018). "Compared with primary tumors, metastatic tumors more often displayed ZFHX4, FGFR1, MSI2, HIST1H1C, and TOP1 mutations, while MAPK7 mutations occurred only in primary tumors." (PMID 41301029, 2025). "Mutations in ZFHX4 (p = 0.0392), FGFR1 (p = 0.0436), MSI2 (p = 0.0437), HIST1H1C (p = 0.0467), and TOP1 (p = 0.0497) were significantly more common in metastatic tumors compared to primary tumors." (PMID 41301029, 2025). "TOP1 was found to be enriched in metastatic tumors (90%; 9/10) relative to posterior fossa cases (50%; 10/20) (p = 0.0485, Fisher exact test), and there was a positive correlation between TOP2A and TOP1 expression (p = 0.0472)." (PMID 29869738, 2018).
neutropenia (2 papers, 2015 to 2023). A decrease in the number of neutrophils found in the blood. "The most common adverse effects ≥grade 3 were neutropenia (12%), fatigue (8%) and vomiting (6%), consistent with the toxicity profile of TOP1 inhibitors." (PMID 37488289, 2023).
rhabdomyosarcoma (2 papers, 2018 to 2022). A rare aggressive malignant mesenchymal neoplasm arising from skeletal muscle. "Depletion of UCHL3 was sufficient to reduce TDP1 expression in rhabdomyosarcoma cells to levels comparable to control cells (top) and led to hypersensitivity to the TOP1 poison CPT (bottom)." (PMID 29898404, 2018). "Depletion of UCHL3 in rhabdomyosarcoma cells reduced TDP1 levels and sensitized cells to TOP1 poisons." (PMID 29898404, 2018).
skin cancer (2 papers, 2021 to 2025).
thyroid cancer (2 papers, 2021 to 2025). "We have shown that pY397 FAK is localized in the nucleolus in aggressive thyroid cancer cells where it interacts with nucleolar proteins involved in ribosomal biogenesis including NOP56, TOP1, RPL36, and PRKDC." (PMID 40458728, 2025). "Camptothecin is a DNA topoisomerase I inhibitor that blocks DNA synthesis and down-regulates THBS1 expression in human thyroid carcinoma FTC-133 cells through the JNK/ATF-2 pathway." (PMID 33746571, 2021).
acute leukemia (1 paper, 2021). A clonal (malignant) hematopoietic disorder with an acute onset, affecting the bone marrow and the peripheral blood. "Moreover, clinical trials investigating TOP1 inhibitors for acute leukemia have been reported, showing promising results." (PMID 34201500, 2021).